USP17L9P (ubiquitin specific peptidase 17 like family member 9, pseudogene)
Synonyms: RS447; USP17; USP17A; USP17H; USP17I; USP17J; USP17K; USP17L; USP17M
Gene: Unprocessed pseudogene on chromosome 4 (9,358,383 to 9,359,975, forward strand). Ensembl gene ENSG00000251694.
Diseases named in the same sentence as USP17L9P in open-access papers:
USP17L9P is named in the same sentence as 2 diseases in open-access papers, as found by Europe PMC text mining. Sharing a sentence is not in itself a finding about the gene and the disease.
USP17L9P shares sentences with these, for which no sentence is quoted: breast carcinoma (1 paper); tumor (1).